KIF5B (kinesin family member 5B)
Diseases named in the same sentence as KIF5B in open-access papers (continued):
Sharing a sentence is not in itself a finding about the gene and the disease.
infection (continued). "We and others have recently observed that microtubule motors dynein and the kinesin-1 motor KIF5B are required for HIV-1 uncoating and infection." (PMID 27327622, 2016). "Using this assay, we observed a significant increase in the amount of capsid localized around the perinuclear region in KIF5B and NUP358 knockdown cells relative to control cells at three hours post-infection." (PMID 27327622, 2016). "To understand the functional relevance of KIF5B mediated trafficking of HIV-1 during infection, we measured viral reverse transcription and nuclear import (as measured by 2-LTR formation) products in cells depleted of KIF5B or Nup358 by siRNA using quantitative PCR." (PMID 27327622, 2016). "KIF5B knockdown also prevents the nuclear entry and infection by HIV-1, but does not exert a similar effect on the N74D or P90A capsid mutants which do not rely on Nup358 for nuclear import." (PMID 27327622, 2016). "The observation that these mutants are similarly not dependent on KIF5B for nuclear import and infection suggests that KIF5B and Nup358 act cooperatively to facilitate nuclear entry of the viral complex." (PMID 27327622, 2016). "Infection of HeLa cells transfected with control or KIF5B specific siRNA did not influence the number of PLA puncta observed following infection with WT virus." (PMID 27327622, 2016). "Infection with wildtype virus showed no change in the amount of late reverse transcription products following KIF5B or Nup358 depletion." (PMID 27327622, 2016). "Strikingly, we also observed that depletion of KIF5B did not affect nuclear import or infection by the P90A and N74D mutant viruses." (PMID 27327622, 2016). "To test whether BORC-related lysosome trafficking components mediate BCV trafficking during infection, we analyzed the dynamics of the interaction of BCVs with LAMTOR1 (a central component of mTORC1), the small GTPase ARL8b, and kinesin KIF1b and KIF5b proteins during infection." (PMID 35587649, 2022). "Next, Vero cells, respectively, transfected with control siRNA and KIF5B siRNA were infected with the same amount of PEDV particles at 4°C for 30 min (as 0 h post-infection) for PEDV attachment and then at 37°C for 1 h (as 1 h post-infection) for PEDV internalization." (PMID 33538234, 2021). "The observation that knocking down both Nup358 and KIF5B did not increase the infectivity defect or uncoating defect observed when these proteins were depleted individually is consistent with these proteins acting at a similar step in infection." (PMID 27327622, 2016).
adenocarcinoma (7 papers, 2014 to 2024). A common cancer characterized by the presence of malignant glandular cells. "These and 28 other mutations were detected at a significantly higher prevalence in adenocarcinoma cases including therapy-associated MET exon 14 skipping mutations (3.8% vs 0.8%), EML4-ALK fusions (2% vs 0%), and KIF5B-RET fusions (0.5% vs 0.1%)." (PMID 39664186, 2024). "Interestingly, FOXA2 transcription factor is known to be upregulated in KIF5B-RET fusion adenocarcinomas through RET downstream signaling pathways such as ERK and AKT." (PMID 38132167, 2023). "Here, we also, for the first time, reported a 43-year-old female nonsmoker diagnosed with stage IV poorly differentiated adenocarcinoma of lung harboring KIF5B–RET fusion with highly positive PD–L1 staining (65%)." (PMID 32587276, 2020).
skeletal dysplasia (3 papers, 2019 to 2024). Any Mendelian diseases that affects growth and development of the skeleton. "This study expands the clinical spectrum of KIF5B-related disorder and informs on the mechanism of pathogenic variants in kinesin-1 in skeletal dysplasia." (PMID 37934770, 2023). "Loss of KIF5B in the cartilage leads to growth plate abnormalities, bone growth retardation and dwarfism, reminiscent of human skeletal dysplasia in mice, which suggests a potential connection between kinesin-1 and human skeletal diseases." (PMID 31636894, 2019). "Mutations in KIF5B, KIF7, KIF10, and KIF22 kinesin proteins lead to skeletal dysplasia with various severity of clinical features and overlapping phenotypes." (PMID 38646780, 2024).
neurodegenerative disease (1 paper, 2022). A disorder of the central nervous system characterized by gradual and progressive loss of neural tissue and neurologic function. "Magi2, Kif5b, Sqstm1 and Rap1a are associated neuronal development and neurite outgrowth, and some have previously been implicated in the pathogenesis of neurodegenerative diseases." (PMID 36089582, 2022).
KIF5B also shares sentences with these, for which no sentence is quoted: cervical cancer (4 papers); colorectal cancer (2); gastric cancer (2); Anxiety (1); bent bone dysplasia (1); bone metastasis (1); brain tumors (1); breast tumors (1); Cerebral ischemia (1); cholangiocarcinoma (1); clear cell renal cell carcinoma (1); cognitive deficits (1); gastrointestinal stromal tumor (1); glioblastoma (1); hepatocellular carcinoma (1); immune deficiency (1); infantile hemangioma (1); large cell lymphomas (1); metabolic disorders (1); metanephric adenoma (1); muscular dystrophy (1); myopathy (1); neurological disorders (1); oral squamous cell carcinomas (1); retinoblastoma (1); skeletal diseases (1); skin cancer (1); soft tissue tumors (1); synovial sarcoma (1).